PARP1 (poly(ADP-ribose) polymerase 1)
Diseases named in the same sentence as PARP1 in open-access papers (continued):
Sharing a sentence is not in itself a finding about the gene and the disease.
lung carcinoma (continued). "After the knockdown of PARP1, the effect of USP5-dependant progression in lung cancer cells will be terminated." (PMID 37060095, 2023). "We found that the expression of PARP1 was higher in lung cancer–MSCs, and the SFPQ knocking down reduced the levels of PARP1 and γ2HAX in NSC lung cancer -MSCs." (PMID 35707369, 2022). "In order to determine if SFPQ affects DNA damage and repair in NSC lung cancer -MSCs, we knocked down SFPQ with SFPQ shRNA, and then we measured the levels of DNA repair marker PARP1 and DNA damage marker γ2HAX." (PMID 35707369, 2022). "In lung cancer cells, not only ERK phosphorylation but also total ERK protein levels were decreased upon inhibition of ADP-ribosylation or PARP1-siRNA treatment." (PMID 34725336, 2021). "We found one SNP or allele may not fully explain the role of PARP1 in lung cancer." (PMID 33284833, 2020). "In this study, we obtained eight lung cancer-related genes (CDC25C, TWIST1, HIF1A, DNMT1, PARP1, CDKN1A, CCNB1, and BIRC5) as seed nodes, using an RWR algorithm analysis to prioritize lung cancer related genes." (PMID 33193600, 2020). "In our population with a majority of European ancestry and specifically in NSCLC, we found PARP1-rs3219073 alone may not be associated with lung cancer, but rs3219073, rs1805415, and rs1805414 together could differentiate the lung tumor and normal tissues in MDR analysis." (PMID 33284833, 2020). "Our result showed that PARP1 and HIF1A have 41 known lung cancer-specific (hypergeometric test p-value < 1.0E–20) and 30 clinically relevant (p-value = 0.04) synthetic lethal interactions between their OCRs." (PMID 31097707, 2019). "Taken together, these results strongly suggest that PARP1 and HIF1A are effective combinatorial therapeutic targets for lung cancer." (PMID 31097707, 2019). "CEP plus TRAIL induced the sub-G1 population and PARP-1 cleavage in other renal cell carcinoma (ACHN, A498), hepatocellular carcinoma (SK-Hep1), and lung carcinoma (A549) cells." (PMID 30360403, 2018). "In summary, inhibitors of CDK4/6 sensitize lung cancer cells to oxidative stress-inducing anticancer drugs by creating a functional link between RB1, PARP1, and OGG1." (PMID 29306194, 2018). "There was also significant reduction of PARP (Poly(ADP-ribose) polymerase-1) and the augmentation of cleaved-PARP in lung cancer cells treated with 10–20 μg/mL." (PMID 28532227, 2017). "This high prevalence of autoantibody to PARP1 (22.4%) was notable, and meanwhile there was very low frequency of autoantibodies to BRCA1 (4.3%) and to BRCA2 (1.1%) in lung cancer sera." (PMID 25865228, 2015). "Together, USP5 could promote the progression of lung cancer cells by mTOR signaling pathway and interacting with PARP1, indicating that USP5 may become a new target for lung cancer treatment." (PMID 37060095, 2023). "Notably, USP5 is highly expressed in lung cancer, USP5 overexpression promoted the proliferation and migration in the lung cancer cell lines, H1299 and A549, while knockdown of USP5 inhibited these via regulating the PARP1-mediated mTOR signaling pathway." (PMID 37060095, 2023). "Several studies also showed that some microbes could induce lung cancer by upregulating the ERK and phosphoinositide 3-kinase (PI3K) signaling pathway or pol (ADP-ribose) polymerase 1 (PARP1)." (PMID 35010784, 2022). "A pattern of cell death characterized by PARP-1 cleavage without caspase activation has been recently described by Hino and co-workers in lung cancer cell lines exposed to abemaciclib." (PMID 36497412, 2022). "Similarly, in breast and lung cancers, inhibition of the receptor tyrosine kinase c-MET reduced PARP1 phosphorylation and improved therapeutic responses to PARP inhibitors." (PMID 35205643, 2022).
lung carcinoma (continued). "According to published Western Blots (WB) results, the level of PARP-1 expression in VERO cells is considerable, with it being similar to that in human epithelial cell lines, such as HEK293 (embryonic kidney), A549 (lung carcinoma), or HEp-2 (laryngeal carcinoma)." (PMID 33167404, 2020). "In lung cancer sera, 22.4% (21/94) was shown to have autoantibody to PARP1, 4.3% (4/94) was shown to BRCA1, 1.1% (1/94) was shown to BRCA2, 4.3% (4/94) was shown to PARP1 and BRCA1, and 0% (0/94) was shown to PARP1 and BRCA2." (PMID 25865228, 2015). "The lung cancer cells treated with USP5 could not effectively disregard the effects of PARP1 knockdown on their progression, inferring that the USP5 might function effectively combined with PARP1." (PMID 37060095, 2023). "Our finding not only suggested that BDH1 might be useful as a novel biomarker and therapeutic target for lung cancer metastases, but also imply that PARP1‐mediated AMPK‐mTOR signalling pathway might play a critical role in BDH1‐induced autophagy and lung cancer proliferation and metastases." (PMID 36919822, 2023). "Overall, this study suggests that Parp-1 rather than Parp-2 inhibition seems to exert more beneficial effects on muscle-related miRs expression of cachectic limb muscles in this specific mouse model of lung cancer cachexia." (PMID 32325796, 2020). "The carcinogenesis role of PARP1 in lung cancer is still not clear." (PMID 33284833, 2020). "A gene PARP1 with high betweenness value except for the famous oncogene with high connected degree was found, which indicated it played at a relatively core role in NSCLC gene network, yet it was unknown of the role of this gene in lung cancer." (PMID 29152079, 2017). "The reason for this difference might be that there was no synthetic lethal interactions between PARP1 and BRCA1/BRCA2 in lung cancer or there might be existed other types of synthetic lethal interactions, which is supported by recent studies." (PMID 25865228, 2015).
glioblastoma (79 papers, 2010 to 2025). The most malignant astrocytic tumor (WHO grade IV). "Veliparib (PARP1 inhibitor) associated with temozolomide represents an effective method in glioblastomas." (PMID 40002588, 2025). "The same treatments also decreased the glycosylated fraction of GLUT4-eGFP fusion protein associated with the vesicles, further suggesting that in glioblastoma cells PARP1 has a role in GLUT/SLC2As trafficking." (PMID 32443613, 2020). "Overexpression of PARP-1 and its constitutive activation is found to be associated with self-renewal properties of glioblastoma-initiating cells." (PMID 28346397, 2017). "This study was aimed at the development of a novel diagnostic tool for glioblastoma through the synthesis of a small molecule based on radioiodinated poly(ADP-ribose)polymerase 1 (PARP1) targeted tracers." (PMID 26337803, 2015). "Similarly, HECTD3-mediated K63-linked polyubiquitination of PARP1 results in DNA lesions in glioblastoma cells, increasing apoptosis vulnerability." (PMID 39528473, 2024). "There is increased pan-cancer specific interest in repurposing the poly adenosine diphosphate-ribose polymerase-1 (PARP-1) inhibitor, olaparib, for newly diagnosed or recurrent isocitrate dehydrogenase wild type glioblastoma." (PMID 39433869, 2024). "In conclusion, we would like to highlight that Polθ inhibition used in combination with PARP1 or RAD52 inhibition has great potential to kill glioblastoma cells, and shows a synthetic lethal effect, while sparing normal astrocytes." (PMID 39273083, 2024). "Inhibition of Polθ or PARP1 or RAD52 produces a significant reduction in glioblastoma cell viability in comparison to the untreated control." (PMID 39273083, 2024). "Primary tumor RNA sequencing data was used to determine PARP-1 as a target in the glioblastoma infiltrative margin." (PMID 39433869, 2024). "The findings of the PPI network analysis suggested that the key targets of naringin in the chemosensitization of glioblastoma would be PARP-1, MGMT, and caspases." (PMID 39148542, 2024). "For instance, PARP1 is overexpressed in glioblastoma, high-grade astrocytomas, medulloblastoma, and pediatric ependymoma." (PMID 39598347, 2024). "The discovery of upregulated PARP1 in glioblastoma tumor stem cells is a significant result of the research." (PMID 39598347, 2024). "The results showed the specific binding of the I2-PARPi tracer to PARP1 indicating the potential of this tracer for glioblastoma detection." (PMID 39355049, 2023). "Recent evidence suggests that supplementation of standard therapy with quercetin enhances the efficacy of treatment of experimental glioblastoma by inducing apoptosis through caspase-3 and PARP-1 cleavage, and suppressing PI3K–Akt activation." (PMID 35883021, 2022). "By enhancing apoptosis through inducing caspase-3 and PARP-1 cleavage and suppressing activation of the Akt pathway, quercetin supplements standard therapy with improved efficacy in treating experimental glioblastoma." (PMID 35883021, 2022). "Recently, the therapeutic efficacy of an iodine-123-labelled poly(ADP-ribose) polymerase 1 (PARP1) inhibitor ([123I]I-MAPi) in glioblastoma models was presented." (PMID 33906122, 2021). "The combination of these drugs in VRK1 depleted cells resulted in an increase of glioblastoma cell death detected by annexin V and the processing of PARP-1 and caspase-3." (PMID 34195200, 2021). "We have shown that VRK1 depletion sensitizes tumor cells to two types of pharmacological treatments, temozolomide, a drug used in glioblastoma, and olaparib, an inhibitor of PARP-1 that is in use for the treatment of tumors with BRCA1 mutations." (PMID 34195200, 2021). "When PARP1 expression levels were considered, amalgams with LCu or HCu caused DNA damage to human DBTRG glioblastoma cells, but Se decreased the extent of the damage." (PMID 33624687, 2021). "Our previous observations in glioblastoma cell lines indicate that PARP-1 inhibition potentiates CLytA-DAAO-induced cell death." (PMID 33198289, 2020).
glioblastoma (continued). "Our results are consistent with a previous study that showed that galangin stimulates apoptosis in glioblastoma multiforme cells and up-regulates the levels of cleaved PARP-1 and cleaved caspase-3,7." (PMID 32235536, 2020). "The compounds with the best pharmacokinetics were radioiodinated and evaluated in culture and orthotopic mouse models of human glioblastoma for PARP1 specificity." (PMID 32194409, 2020). "18F-PARPi is an olaparib-based PET imaging agent that exhibits high specificity for PARP1 in mouse models of orthotopic glioblastoma, diffuse intrinsic pontine glioma, and small-cell lung cancer." (PMID 32194409, 2020). "This implies that PARP-1 is essentially participating in DNA damage repair in glioblastoma cell lines." (PMID 33198289, 2020). "Using a colorimetric assay and purified PARP1 we found that in vitro the addition of 10 μg of total proteins purified from the cytosol of Hu197 human glioblastoma cells inhibited PARP1 activity." (PMID 32443613, 2020). "In glioblastoma cells, PARP1 inhibitor veliparib mimics glucose starvation in enhancing glucose uptake." (PMID 32443613, 2020). "Different PARP-1 gene expression proteins have been observed in various tumors such as lung, ovarian, endometrial, skin, and glioblastoma." (PMID 32850156, 2020). "Radiotherapy in glioblastoma multiforme patients’ lead to the upregulation of PARP1 mediated repair of DNA damage in glioblastoma cancer stem cells." (PMID 31109041, 2019). "PARP-1 (full length) was well expressed in all experimental conditions, confirming its well-known overexpression in glioblastoma and its involvement in chemoresistance." (PMID 30678338, 2019). "Our study showed that silibinin treatment not only inhibited the metabolic activities of glioblastoma cells but also promoted their apoptosis through the regulation of caspase 3 and PARP-1 in concentration- and time-dependent manners." (PMID 29780826, 2018). "Various clinical trials are evaluating the PARP1 inhibitor (Olaparib) in combination with radiotherapy and/or temozolomide in glioblastoma patients subdivided according to the MGMT methylation status." (PMID 30279357, 2018). "Contrary to glioblastoma cells, neurons don't seem to express PARP-1 and are low replication cells: this aids to protect healthy tissues by radiosensitizing only tumor cells." (PMID 28978184, 2017). "In an orthotopic glioblastoma model, [18F]PARPi was also shown to selectively accumulate in PARP-1-expressing U251-MG tumours, indicating the ability of this radiotracer to pass through the blood–brain barrier." (PMID 28058462, 2017). "Our previous work has shown that small molecular PARP1 inhibitors, like the fluorescent PARPi-FL, accumulate in the nucleus of glioblastoma cells at high concentrations and with high specificity." (PMID 26337803, 2015). "The percent PARP1 positive area in both glioblastoma models was similar, with 42.0 ± 10.4 % and 41.5 ± 11.0 % for U251 MG and U87 MG, respectively (for healthy brain, PARP1 positive area was 2.7 ± 1.3 %)." (PMID 26337803, 2015). "This is particularly apparent in mouse models of glioblastoma, where tumor tissue is overexpressing PARP1, whereas healthy brain tissue has very low levels of the enzyme." (PMID 26337803, 2015). "This PARP1 is a biomarker that is overexpressed in glioblastoma tissue, but has only low expression levels in the healthy brain (Neoplasia 16:432-40, 2014)." (PMID 26337803, 2015). "Immunofluorescence PARP1 antigen detection in histological sections of U251 MG and U87 MG glioblastoma xenografts showed an overexpression of PARP1 compared to healthy brain tissue." (PMID 26337803, 2015). "Based on our successful optical PARP1 imaging agents, we chose a 2H-phthalazin-1-one scaffold previously used by us for targeting glioblastoma cells." (PMID 26337803, 2015). "In a panel of primary glioblastoma lines, sensitivity to PARP1 inhibition correlated with the levels of EGFR activation and oxidative stress." (PMID 20532243, 2010).
glioblastoma (continued). "Moreover, glioblastoma have been shown to be therapeutically vulnerable to PARP1 inhibition, and olaparib effectively increased the radiosensitivity of glioblastoma cells in vitro." (PMID 40661778, 2025). "RNA-sequencing confirmed PARP-1 as a viable therapy target in glioblastoma infiltrative disease." (PMID 39433869, 2024). "We discuss how the recent advances in our understanding of the genetic determinants of TMZ toxicity might lead to new approaches for the treatment of glioblastomas by inhibiting PARP1 and other enzymes involved in the repair of alkylation damage (e.g., APE1)." (PMID 39011394, 2024). "Unfortunately, we were unable to detect the cleaved PARP-1 protein in human glioblastoma cells." (PMID 37509230, 2023). "This may be due to the different species origin and specificity of the antibody used for the detection of PARP-1 in human and rat glioblastoma cell samples." (PMID 37509230, 2023). "18F-PARPi-FL, as a bimodal fluorescent/PET agent, is used for PARP1 imaging in glioblastoma cells." (PMID 39355049, 2023). "Moreover, other proteins in the pathway, for instance PARP1, have highly specific inhibitors that are currently tested alone or in combination with temozolamide against glioblastoma, both in experimental models and human subjects." (PMID 32443613, 2020). "Furthermore, cytosol extracted from glioblastoma cells inhibits PARP1 enzymatic activity in vitro while immunodepletion of SHC3 from the cytosol significantly relieves this inhibition." (PMID 32443613, 2020). "PARP1-specific uptake was demonstrated in glioblastoma xenografts." (PMID 32194409, 2020). "Furthermore, the number of dead cells was noticeably increased after 48 h of treatment with 100 μM canavanine, which coincided with a progressive accumulation of the cleaved forms of PARP1 and caspase 3 after 48 h of treatment in both glioblastoma cell lines." (PMID 33008000, 2020). "These experiments also revealed that inhibition of MTH1 activity in-itself could increase the sensitivity of glioblastoma to treatment with PARP-1." (PMID 29938005, 2018). "PARP1 is overexpressed in a variety of cancers, including glioblastoma." (PMID 28654422, 2017). "Overexpression of PARP1 exists in various cancers, including glioblastoma (GBM)." (PMID 28654422, 2017). "This drastic difference in expression levels was also observed in human tissue and led us to believe that a non-invasive imaging agent for PARP1 could be used to detect glioblastoma with high signal/noise ratios." (PMID 26337803, 2015). "The PARP1 positive area in glioblastoma slides was increased by a factor of 15.8 ± 8.1." (PMID 26337803, 2015). "However, in glioblastoma cells, loss of PARP1 expression by CRISPR-KO did not sensitize MSH6-mutant tumor cells to the alkylating agent temozolomide (TMZ), suggesting a more complicated role for PARP in response to alkylating agents." (PMID 34198612, 2021). "ROS and RNS, by damaging DNA, can activate PARP-1 which appears a key mediator in malignancy maintenance in various cancers, including Glioblastoma Multiform (GBM)." (PMID 30678338, 2019). "Immunohistochemistry bore out the first hypothesis, showing that in an experimental model of radiation necrosis, mice did not develop elevated PARP1 expression as compared to contralateral or treatment-naïve brain, while glioblastoma xenografts expressed high levels of PARP1 in tumor cell nuclei." (PMID 29974335, 2018). "RT in GBM patients’ lead to upregulation of PARP1 mediated repair of DNA damage in glioblastoma CSCs." (PMID 30327965, 2018). "Our results showed decreased gene expression of PARP1 and PARP2 in MDR glioblastoma cells, while MDR NSCLCs exhibited increased mRNA expression of these genes." (PMID 40006556, 2025). "The synthetic lethality achieved by combined inhibition of Polθ with other DNA repair proteins, such as PARP1 or RAD52, have an even greater effect on defeating glioblastoma; however, it needs to be studied in the broader context of its toxicity." (PMID 39273083, 2024).